IL10 (interleukin 10)
Diseases named in the same sentence as IL10 in open-access papers (continued):
Sharing a sentence is not in itself a finding about the gene and the disease.
colitis (continued). "Inversely, inhibition of these proteases improved intestinal barrier dysfunction and prevented colitis in these mice as well as in Phocaeicola vulgatus monocolonized, IL-10 deficient mice." (PMID 38715051, 2024). "Mice studies showed that knockout of SERT exacerbates colitis and intestinal inflammation in IL-10 deficient mice." (PMID 39249550, 2024). "As IL10‐deficient mice possess a reduced ability to regulate the inflammatory response, the result is an acceleration of colitis development." (PMID 38992956, 2024). "Defects in IL-10 signaling are associated with severe infantile enterocolitis in humans, and mice deficient in IL-10 or its receptors develop spontaneous colitis." (PMID 37314833, 2023). "The DSS-induced colitis model only reflects the immunological situation during acute inflammation, while Il-10-deficient mice are useful in determining long-term effects of ongoing inflammatory initiated spontaneously." (PMID 37834303, 2023). "Loss of IL-10 or IL-10 signaling corresponds with early-onset, severe human intestinal disease and with development of colitis in mouse models." (PMID 36538527, 2023). "In Il-10-spontaneous colitis, Ogr1-deficient mice presented significantly decreased, and Tdag8-deficient mice had increased inflammation." (PMID 37834303, 2023). "G protein-coupled receptor 120 (GPR) is implicated in regulating CD4+ T cell production of IL-10 in the gut to inhibit the development of colitis, which identifies GPR 120 as a potential therapeutic target." (PMID 38137450, 2023). "TRPM8-deficient mice exhibit increased susceptibility to colitis, a phenotype rescued by systemic IL-10 expression." (PMID 37404813, 2023). "A mixture of lactobacillus paracasei and reuteri has been reported to reduce the amount of mucosal pro-inflammatory cytokines leading to an attenuation in the colitis of IL-10-deficient mice infected with helicobacter hepaticus." (PMID 36611977, 2023). "For this purpose, we assessed the impact of SFB colonization on colitis development in IL10-deficient (Il10−/−129Sv) mice, known to develop Th1/Th17-related and microbiota-dependent colonic inflammation." (PMID 37004103, 2023). "IL-10 is critical in controlling infections in the colon as IL-10-deficient mice developed severe and sustained diarrhea and colitis within 1–2 weeks after infection." (PMID 37111225, 2023). "Lactobacillus plantarum 299v, in a study in mice deficient in IL-10, relieved colitis and reduced the levels of IL-12 and IFN-γ." (PMID 38138886, 2023). "T cell specific-HK2 deficiency partially recovers intestinal inflammation in a spontaneous colitis model of IL-10 knockout (KO) mice, although HK2-deficient CD4+ T cells appear to have normal proliferation, viability, activation and differentiation in vitro." (PMID 37809060, 2023). "The “virus + susceptibility gene” model of colitis is the IL10−/− mouse is confounded somewhat because part of the “susceptibility” is related to the development of MMTV infection." (PMID 36869359, 2023). "The pace of colitis development slows down with the treatment of resveratrol in IL-10-deficient mice accompanied by MDSC multiplication and reduced colitis-associated cytokine production." (PMID 37875976, 2023). "Another study found that the abundance of A. muciniphila increased significantly in the mouse intestines after worsening of spontaneous colitis caused by NLRP6 gene knockout in IL-10−/− mice, and that A. muciniphila administration orally worsened the colitis." (PMID 36937258, 2023). "Different models of acute or chronic colitis were used (DSS- or IL-10-deficient mice), and different doses of HMOs, alone or mixed, were administered, either preventively or curatively." (PMID 38140362, 2023). "One available study showed that inhibition of PARP2 expression by antisense nucleotide was also found effective in ameliorating colitis in IL-10 deficient mice." (PMID 37457706, 2023).
colitis (continued). "Animals with an IL-10 deficiency develop spontaneous colitis due to their inability to tolerate the intestinal microbiome." (PMID 37256109, 2023). "Increased NF-κB expression in mucosal macrophages is accompanied by increased expression of TNF-α and chemokines in TNBS- or IL-10-deficient-induced colitis mice." (PMID 36926182, 2023). "Our data as well as other reports suggest that macrophages are key in eliciting colitis in IL10 deficiency." (PMID 37834303, 2023). "Development of colitis in IL-10KO mice is driven by expansion of Th1 and Th17 cells and has historically been attributed to the loss of IL-10 derived from Foxp3+ intestinal Tregs." (PMID 37314833, 2023). "It is interesting to note that in the IL10 deficiency model (spontaneous colitis) the pro-inflammatory effects of TDAG8 deficiency became clearly visible and highly significant." (PMID 37834303, 2023). "Tr1 cells prevent colitis in adoptive transfer models, and pathogenic colitis-inducing Th17 cells are suppressed by both Foxp3+ and Foxp3- IL10-producing CD4+ T-cells." (PMID 37654482, 2023). "A. muciniphila has additionally been associated with a decreased mucus layer and spontaneous colitis in GF Il10−/− mice." (PMID 36413219, 2023). "The in vivo investigations revealed the treatment effects of si‐circPRKAR1B and si‐METTL3 in colitis models of IL‐10‐deficient mice." (PMID 37679886, 2023). "Particularly in the gastrointestinal tract, IL10 is closely associated with the development of colitis." (PMID 37373511, 2023). "The aim of this study was to characterize the effect of IL-10 deficiency on the MC phenotype and its activation via PRRs in stages before and after the development of colitis in a murine model of IBD." (PMID 37373041, 2023). "Dextran sodium sulfate-induced colitis model and IL-10-deficient mouse model are well-known conventional in vivo inflamed-epithelium model systems." (PMID 37435069, 2023). "Genetic ablation of Il10 demonstrated the critical role of Il10 in regulating inflammation, as IL-10-deficient mice spontaneously developed colitis." (PMID 37483629, 2023). "The piroxicam-accelerated colitis in interleukin-10-deficient (IL10−/−) mice is another model where piroxicam (an NSAID) uniformly initiates chronic colitis in IL10−/− mice through epithelial barrier disruption and penetration of luminal bacteria." (PMID 37189818, 2023). "They observed that the altered microbial community was transmitted to the IL‐10‐deficient offspring which resulted in the development of markedly increased colitis." (PMID 35212478, 2022). "Il10-deficient mice spontaneously develop cecitis (typhlitis) and colitis, a process that can be experimentally accelerated through oral administration of non-steroidal anti-inflammatory drugs such as piroxicam." (PMID 36434690, 2022). "The results reported herein demonstrates that intestinal barrier dysfunction is an early event in the natural history of colitis in IL-10 deficient mice, preceding the development of overt inflammation, as it seems to occur in human CD." (PMID 36699599, 2022). "Mice deficient in either IL-10 or its receptor develop spontaneous colitis, and became one of the most widely used animal models for studying IBD pathogenesis." (PMID 35967333, 2022). "Among these, interleukin (IL)-10 is critical for the establishment of intestinal homeostasis, as mutations in components of the IL-10 signaling pathway result in spontaneous colitis." (PMID 35840681, 2022). "The microbiota also promoted the development of colitis when used to colonize IBS-prone interleukin 10-deficient mice." (PMID 35873168, 2022). "In this study, we investigated mechanisms of food additive-induced impairment of mucus barrier integrity in the microbe-dependent interleukin-10 deficient (IL10KO) mouse colitis model." (PMID 35359925, 2022).
colitis (continued). "The expansion of this bacterium was associated with a proinflammatory TH1 immune response and with a greater number of genetically susceptible IL-10−/− mice developing colitis." (PMID 35323020, 2022). "Dietary fat increases taurocholic acid production in the colon, leading to dilation of Bilophila wadsworthia and colitis in interleukin-10 deficient mice." (PMID 36523998, 2022). "It has also been reported T. halophilus significantly augmented the gene expressions of IL-10, and IL-10 deficient mice have been used as a model reflecting the characteristics of colitis." (PMID 35741032, 2022). "vulgatus had significantly reduced colitis-associated colon tumor multiplicity compared with conventional IL-10−/− mice." (PMID 36376984, 2022). "Administration of IL-10-secreting Lactococcus lactis caused a 50% reduction in colitis in mice treated with DSS and prevented the onset of colitis in IL-10(-/-) mice." (PMID 35082553, 2022). "Daily intragastric delivery of L. lactis modified to contain the murine IL-10 prevented the onset of colitis in IL-10-deficient mice more efficiently than systemic delivery of recombinant murine IL-10." (PMID 36012618, 2022). "Correspondingly, B. wadsworthia occurrence, as well as TCA supplementation, are also associated with colitis development in IL-10−/− mice." (PMID 35954180, 2022). "Mannose treatment attenuates intestinal barrier damage in two mouse colitis models, dextran sodium sulfate (DSS)-induced colitis and spontaneous colitis in IL-10-deficient mice." (PMID 35974017, 2022). "IL-10 is an essential anti-inflammatory cytokine, and IL-10-deficient mice have been reported to develop colitis spontaneously." (PMID 35672695, 2022). "Protection was most pronounced in Il10−/− mice, which otherwise exhibited profound weight loss and aggravated colitis following piroxicam administration and AIEC infection." (PMID 36094114, 2022). "In a mouse model of colitis where IL-10-deficient mice were infected with H. hepaticus, the combination of L. paracasei 1602 and L. reuteri 6798 reduced mucosal inflammatory cytokines TNF-α and IL-12 and also reduced intestinal inflammation." (PMID 35464397, 2022). "Selective deficiency of IL-10 in Foxp3+ Tregs results in spontaneous colitis, suggesting that IL-10 is a key effector molecule for Treg-mediated tissue regeneration and protection." (PMID 35572535, 2022). "The objective of this work is to study these parameters in the natural history of colitis in IL-10 deficient mice (IL-10−/−)." (PMID 36699599, 2022). "In the IL10KO colitis model, loss of IL-10 signaling removes inhibition of pro-inflammatory signaling, resulting in an influx of immune cells into the colon." (PMID 35359925, 2022). "In this study, using Il10-/- mice, we demonstrate that exposure to heavy-ion radiation is associated with a higher incidence of colitis and CRC as well as co-activation of β-Catenin and NF-κB signaling." (PMID 36584137, 2022). "Of note, DSS-induced colitis causes human ulcerative colitis-like pathologies, while Il-10−/− mice develop colitis similar to that seen in human Crohn’s disease." (PMID 36408246, 2022). "Accordingly, IL-10R-deficient patients with IBD, display defective functions of MФs as do patients with polymorphisms in the IL-10 promoter, while mice deficient in IL-10 or IL-10R develop spontaneous colitis." (PMID 36189323, 2022). "IL-10 deficient mice develop spontaneous colitis, and IL-10–/– mice are an increasingly employed animal model for the study of IBD." (PMID 35529468, 2022). "In genetically susceptible Il10-/- mice, diet-induced blooming of Bilophila wadsworthia promotes the pro-inflammatory Th1 immune response and an increased incidence of colitis." (PMID 35967333, 2022). "Odoribacter strains have beneficial effects associated with their ability to produce SCFAs or induce IL-10 in a mouse colitis model." (PMID 36687706, 2022).
colitis (continued). "For example, miR-10a has been shown to suppress CD4+ T cell production of IL-10, favoring the induction of more severe colitis in genetically predisposed Rag1−/− mice." (PMID 35408838, 2022). "They further showed that the same E. coli strain aggravated colitis or inflammatory arthritis after transplantation into interleukin-10 deficient or K/BxN mice, respectively." (PMID 36104776, 2022). "In a separate experiment antibody blockade of the α4 integrin, which blocks both integrins α4β7 and α4β1 also induced weight loss, hypothermia and colitis in IL-10−/− mice." (PMID 34433904, 2022). "UCC118TM pre-treatment was associated with a significant upregulation of IL-10 levels both at mRNA and protein level at baseline as well as during colitis." (PMID 35889102, 2022). "Previous studies have shown that colitis in IL-10-/- mice is primarily caused by colonic macrophages induced by MyD88 signaling triggered by the intestinal microbiota." (PMID 36713373, 2022). "We further show that mannose can maintain the integrity of intestinal tight junctions in mice with dextran sodium sulfate (DSS)-induced colitis and IL-10-deficient (IL-10−/−) mice with spontaneous colitis." (PMID 35974017, 2022). "A pathogenic role for A. muciniphila in colitis was previously reported in another study that employed the IL-10-deficient mouse model of colitis, while another study reported contradictory findings." (PMID 36704549, 2022). "IL-10 deficient mice used in this work were kept in conventional housing conditions since the development of colitis is microbiota-dependent." (PMID 36699599, 2022). "The beneficial effects of BEVs or Bt in DSS-colitis are associated with increased production of IL-10 in serum, colonic tissue and by peripheral splenocytes which can promote a non-inflammatory status by counteracting pro-inflammatory responses." (PMID 36439842, 2022). "In our novel system, IL-10−/− mice are colonized by Helicobacter hepaticus, a murine gut bacterium that triggers colitis in genetically predisposed hosts." (PMID 35900107, 2022). "E. faecalis was able to promote and maintain colitis in Il10−/− or Il10 gene deficient mice with induction of rectal dysplasia and carcinoma." (PMID 37206892, 2022). "IL-10 deficient mice develop spontaneous colitis that shares features with ulcerative colitis (UC), marked by epithelial cell hyperplasia and transmural inflammation." (PMID 34433904, 2022). "Findings from IL-10-deficient mice revealed the importance of tolerance to commensal bacteria, as they only developed colitis when colonized with intestinal microbes." (PMID 36389662, 2022). "H. hepaticus is a pathobiont, which can cause colitis in Il10-deficient mice only in specific microbial environments." (PMID 36496380, 2022). "Transgenic mouse strains deficient in IL-10 or IL-10R are susceptible to develop spontaneous colitis early in life, which can be reversed by treatment with recombinant IL-10." (PMID 36290283, 2022). "We measured the levels of inflammatory cytokines such as IL-1β, TNF-α, IL-6, and IL-10, which are linked to colitis." (PMID 36456585, 2022). "In summary, dietary supplementation of CS alleviates DSS-induced acute/chronic colitis and IL-10-deficient spontaneous colitis in mice." (PMID 35908039, 2022). "Different environmental communities result in variable disease susceptibility in other mouse IBD models, such as the IL-10-deficient models of acute dextran sulfate sodium (DSS) colitis 12, 13, and the Nlrp6 inflammasome-knockout colitis models." (PMID 35836813, 2022). "The common preclinical murine models of UC include the DSS-induced colitis model, trinitrobenzene sulfonic acid (TNBS)-induced colitis model and IL-10-deficient mouse model." (PMID 36341374, 2022).
colitis (continued). "Commensal fungi-derived mannans can facilitate the transcription of gene il10 and the expression of anti-inflammatory cytokine to decrease susceptibility to colitis in wild-type mice through activating Dectin-2, Dectin-3 and their downstream c-Cbl in DCs." (PMID 35619716, 2022). "It was found that the deficiency of IL-10 and its receptor IL-10R was associated with the occurrence of spontaneous colitis." (PMID 35321324, 2022). "This indicates that the colitis induced by IL-10 deficiency reduced gut microbiota diversity and richness." (PMID 33578830, 2021). "We have investigated MIBE by using an E. faecalis colonized IL10 knockout mouse model for colitis-associated CRC." (PMID 33969420, 2021). "This pathobiont promotes Th1 type immune responses and increases susceptibility to colitis in IL10–/– mice." (PMID 34201611, 2021). "In further studies they found that NLRP6 plays a role in inhibiting the spontaneous colitis in IL-10 deficient mice, probably by inducing the enrichment of Akkermansia muciniphila, a bacterium that can promote development of colitis." (PMID 33808793, 2021). "The species A. parvulum, enriched in pSS patients, was found to have molecular mimicry with Ro6054 and has also been reported to induce pancolitis in colitis-susceptible interleukin-10-deficient mice." (PMID 33707430, 2021). "For instance, mice deficient in the anti-inflammatory cytokines IL-2 or IL-10 develop spontaneous colitis." (PMID 33435303, 2021). "It suppresses colitis symptoms by inhibiting the IL-6/STAT3 signaling pathway in IL-10 deficient mice as well as in an in vitro culture of colonic explants of patients with CD." (PMID 34068714, 2021). "Here, we examined the impact of opioids locally produced within the gut on the development of colitis in IL-10-deficient (IL-10-/-) mice." (PMID 34299013, 2021). "As expected, piroxicam-induced colitis in IL-10-/- mice was associated with a huge increase in inflammatory cytokines within the inflamed colonic tissue." (PMID 34299013, 2021). "Owing to the close association of IL-10 with inflammation, IL-10-deficient mice, which can develop spontaneous colitis, have been widely used as experimental colitis models." (PMID 33578830, 2021). "Another study has shown that interleukin-10-deficient mice treated with DHA presented attenuated characteristics of colitis, mainly due to an enhanced intestinal epithelial barrier function." (PMID 34884896, 2021). "IL-10 is a critical cytokine for the gut homeostasis and IL-10-deficient mice develop spontaneous colitis, but these mice can be rendered tolerant by optimized protocols of antigen feeding." (PMID 35919733, 2021). "In IL-10-/- mice, the spontaneous onset of the colitis has been associated with an increased intestinal permeability, a primary event mimicked by the exposure to piroxicam, a non-steroidal anti-inflammatory drug inducing epithelial cell apoptosis." (PMID 34299013, 2021). "Although the ApcMin/+; Il10−/− mice have been widely used in the colitis-associated CRC study, it is difficult for us to use this model to investigate the two-way roles of IL-10." (PMID 34606408, 2021). "Colonization with E. faecalis causes colitis in Il10−/− mice but the extracellular production of superoxide appears necessary for cancer formation." (PMID 33969420, 2021). "Mesenteric resident bacteria were isolated from mAT and functionally investigated both in the dextran sulfate sodium (DSS) model and in the Il10 gene-deficient (Il10−/−) mouse colitis model to validate their pro-inflammatory roles." (PMID 34814945, 2021). "Nevertheless, Lactobacillus salivarius 433,118 and Bifidobacterium infantis 35,624 were found to attenuate colitis in Il-10-deficient mice." (PMID 33691712, 2021). "As cytokines of the IL-6 and IL-10 families, including IL-6, IL-10, and IL-22, are implicated in supporting intestinal wound healing and immune regulation during colitis, we evaluated the production of these cytokines upon DSS treatment." (PMID 33673239, 2021).